RNU6-1018P (RNA, U6 small nuclear 1018, pseudogene)
Gene: Small nuclear RNA gene on chromosome 20 (41,684,986 to 41,685,091, reverse strand). Ensembl gene ENSG00000252386.
Homologues: Orthologues: chimpanzee U6 (99% identical), pig U6 (75% identical), dog U6 (73% identical). Paralogues in human: RNU6-504P (92% identical), RNU6-66P (81% identical), RNU6-838P (81% identical), RNU6-1209P (80% identical), RNU6-1287P (80% identical), RNU6-1332P (80% identical), RNU6-774P (80% identical), RNU6-797P (80% identical), RNU6-1331P (79% identical), RNU6-189P (79% identical), RNU6-242P (79% identical), RNU6-490P (79% identical), and 1287 more.